GCG (glucagon)
Diseases named in the same sentence as GCG in open-access papers (continued):
Sharing a sentence is not in itself a finding about the gene and the disease.
Hypoglycemia (continued). "Summarily, our results indicate that secretion of glucagon is impaired in islets lacking Vhlh and suggest a likely mechanism for the hypoglycemia in Pdx-1-Creearly;VhlhLoxP/LoxP, Ngn3-Cre;VhlhLoxP/LoxP and Rfx6;VhlhLoxP/LoxP mice." (PMID 23977255, 2013). "The report that glucagon secretion evoked by insulin-induced hypoglycemia is not very different in control mice and in mice lacking insulin receptors in α cells provides additional evidence for a dissociation between insulin and glucagon secretion." (PMID 24315372, 2013). "Under conditions of hypoglycemia the α-cell is electrically active, in part due to a high basal ATP (and consequent inhibition of much of the KATP currents), which allows opening of Ca2+ channels and glucagon exocytosis." (PMID 22969729, 2012). "Although fasting proinsulin is increased, it does not necessarily represent failing graft function, and glucagon response to hypoglycemia improves over time." (PMID 25013624, 2012). "They enhance the actions of incretin, which promotes insulin secretion and suppresses glucagon secretion depending on blood glucose levels, thereby improving blood glucose control without inducing hypoglycemia." (PMID 22867630, 2012). "It is particularly interesting that in normal rats the antagonist did not improve or even decrease the response of glucagon to insulin-induced hypoglycemia." (PMID 22969729, 2012). "When glucagon increases blood glucose, it proves the paradoxical hepatic glycogen content despite hypoglycemia, and it rules out the differential diagnosis of glycogen storage disease." (PMID 21967988, 2011). "The finding that brain knockdown of Bad impairs glycemic and glucagon responses to glucoprivation is consistent with the idea that BAD expression and function in the brain is required for proper hypoglycemia counterregulation and suggests the involvement of central gluco-detection." (PMID 22162752, 2011). "The goal of this study was to identify a modified form of glucagon suitable for prophylactic treatment of hypoglycemia without increasing baseline blood glucose levels." (PMID 20418955, 2010). "nNOS-KO mice that lack GI neurons in the mediobasal hypothalamus (ARC + VMN) showed significantly decreased epinephrine (but not glucagon) responses to hypoglycemia suggesting that VMN GI neurons are involved in the sympathoadrenal cCRR." (PMID 22022208, 2010). "If surgery is not feasible, the hypoglycaemia can be treated with repeated glucagon injections or intravenous glucose." (PMID 16942396, 2006). "Thus, it appears that antecedent hypoglycemia further deteriorates glucagon counterregulation, with or without drug treatment." (PMID 41502124, 2026). "However, the peak glucagon response was delayed in vehicle-treated rats relative to the SSTR2a group, occurring only toward the end of the challenge period and did not prevent hypoglycemia onset." (PMID 41502124, 2026). "This suggests that drug dosing may not elicit a glucagon response only as hypoglycemia develops, but also may raise it, at least transiently, even in the absence of hypoglycemia." (PMID 41502124, 2026). "In contrast, free or hydrolyzed proteins may act as a mild rescue strategy for hypoglycemia, with or without oral carbohydrates, due to their rapid absorption and potent glucagon-stimulating effects." (PMID 41602572, 2026). "Glucagon secretion is dysregulated in T1D, lacking stimulation by hypoglycemia and an inappropriately elevated response to a mixed meal, while in the isolated islets, glucagon stimulation by low glucose appears impaired, but not to arginine, although this finding is not universal." (PMID 41026524, 2025). "This indicates that glucagon secretion may be dysregulated in some PCOS patients, which could have the dual role of countering hypoglycemia while also contributing to hyperinsulinemia via the stimulatory effects of paracrine glucagon signaling on insulin secretion." (PMID 40013621, 2025).
Hypoglycemia (continued). "Mini-dose glucagon (MDG) has been considered as an alternative to oral carbohydrate intake for mild or impending hypoglycemia without breaking the fast; however, current evidence is limited and remains preliminary, derived largely from small pilot studies and limited real-world data." (PMID 41510436, 2025). "A single dose of glucagon does not cover later occurrences of hypoglycemia and raises concerns as it may lead to a rapid increase in BG levels." (PMID 39271918, 2025). "However, hIAPP does not affect the normal function of glucagon, and glucagon can still play a normal role in hypoglycemia." (PMID 40109329, 2025). "Earlier investigations showed that β-adrenoceptor blockade counter regulates decreased plasma glucose concentration after insulin-induced hypoglycemia but does not interfere with other hormonal (e.g., cortisol, glucagon, and growth hormone) responses to hypoglycemia." (PMID 39640497, 2024). "A notion has been proposed that the primary physiological function of glucagon may not lie in the correction of hypoglycemia, and significant elevation of the blood glucose level by glucagon is only observed with pharmacological doses of the peptide." (PMID 39217353, 2024). "Importantly, in vivo, glucagon releasefrom micelles only occurred at or below the counter-regulatory threshold,with no release observed under moderate hypoglycemia or normoglycemicconditions." (PMID 39634211, 2024). "The controller output of the proposed control method was always non-negative, no excessive controller or algorithm were needed to infuse glucagon or glucose to avoid hypoglycemia and this significantly enhances the simplicity of the design and can reduce complexity and cost." (PMID 38186949, 2024). "In the current study, the increased time before hypoglycemia onset, and the decreased incidence of hypoglycemia following SSTR2 antagonist treatment (PRL-2903) was accompanied by a corresponding increase in plasma glucagon level and a decrease in liver glycogen content (p = 0.08)." (PMID 38510652, 2024). "While glucagon is normally released in response to hypoglycemia, stimulating hepatic glucose output, after RYGBP, the postprandial glucagon response among patients with and without hypoglycemia is identical, indicating a dysregulated a-cell response to hypoglycemia." (PMID 39200136, 2024). "In the final regression models, M-value was overall more strongly associated (negative coefficients) with glucagon (AUC), cortisol, and ACTH responses to hypoglycemia than other metabolic parameters, although the coefficient was not significant with regard to glucagon AUC." (PMID 37708362, 2024). "Adequate glucagon secretion from α-cells is needed so that hypoglycemia does not occur." (PMID 38776022, 2024). "In addition, hypoglycaemia seemed to be explained by a temporal mismatch between glucose and insulin levels rather than by an impaired glucagon response." (PMID 37720541, 2023). "In individuals without diabetes, hypoglycemia is usually countered by a highly integrated defense system which includes reduced insulin secretion, increased release of glucagon, glucocorticoids, epinephrine, norepinephrine, and GH, and stimulation of the sympathetic nervous system." (PMID 37334290, 2023). "Glucagon and insulin dual-hormone systems, without meal announcements or with simple meal announcements, have been found to reduce both hyperglycaemia and hypoglycaemia compared to conventional insulin pump therapy." (PMID 37289734, 2023). "Whereas fasting-induced peripheral insulin resistance might initially buffer against a decline in plasma glucose by reducing peripheral glucose uptake, accompanying reductions in glucagon and EGP during hypoglycemia would be expected to protract the time to recovery." (PMID 37166980, 2023).
Hypoglycemia (continued). "Recently published and ongoing clinical trials have shown promising results in using soluble glucagon for treatment of non-severe hypoglycemia, regardless of whether glucagon has been delivered through automated pumps or via pen-injections." (PMID 36755913, 2023). "Additionally, no changes were observed in 4-hour fasting glucagon or glucagon secretion after insulin-induced hypoglycemia." (PMID 37140984, 2023). "Therefore, glucagon is removed by HD in a manner independent of plasma glucose levels, suggesting an inability to respond to HD-related hypoglycemia." (PMID 37445782, 2023). "Even when youth develop T1D, their glucagon release in response to hypoglycemia appears to be altered early after onset (the first year), and adults with T1D who have continued to make small amounts of their own insulin also have impaired and/or absent glucagon release when hypoglycemia occurs." (PMID 36992764, 2022). "Thus, the elevation of both insulin and glucagon after GPR40 activation may be a mechanism to harmonize between the uptake of energy in the forms of FFAs and the prevention of hypoglycemia under the intake of HFD." (PMID 36246919, 2022). "When high fat diet (HFD) without sufficient glucose is consumed, hypoglycemia may occur, provided that glucagon does not elevate while insulin secretion increases." (PMID 36246919, 2022). "Indeed, inactivation of both α1 and α2 subunits of AMPK in VMN neurons suppresses GI neuron activity in this nucleus but does not impair hypoglycemia-induced glucagon secretion." (PMID 36180454, 2022). "Interestingly, despite the severe impairment in glucose sensing and glucagon secretion, this did not result in severe hypoglycaemia in gluACC1KO mice (relative to controls) after fasting or insulin injection." (PMID 35304577, 2022). "In T1D patients, hypoglycemia may not trigger a typical glucagon response, and exogenous glucagon can be needed to treat severe hypoglycemia." (PMID 36557261, 2022). "In this sense, glucagon secretion is augmented up to 2-fold by variation of glucose levels, but it is markedly increased up to 10-fold by the amino acids glutamine, arginine, and alanine, indicating that hypoglycemia is not the strongest inducer of glucagon secretion by α cells." (PMID 36145148, 2022). "Glucose course after glucagon injection might mimic an insulin-induced hypoglycemia state, characterized by rapid decrease of glucose levels, but without leading to absolute hypoglycemia." (PMID 35723775, 2022). "Metabolic evaluation of hypoglycemia showed a typical profile of hyperinsulinemic hypoglycemia (glucose 37 mg/dL [2 mmol/L], insulin 6.1 mU/L, betahydroxybutyrate [BHB] 0.15 mmol/L, plasma glucose increased from 40 to 79 mg/dL [2.22 to 4.38 mmol/L] on glucagon administration)." (PMID 35897673, 2022). "Furthermore, the LIGHTNING study also used a definition to specifically capture severe hypoglycaemias, including inpatient/ED, ICD‐9‐CM/ICD‐10‐CM code relating to hypoglycaemic coma, plasma glucose <54 mg/dL, intramuscular glucagon administration, and ‘severe’ mentioned in the EMR." (PMID 34807513, 2022). "However, in studies investigating the potential benefit of adding glucagon to artificial pancreas devices, glucagon has been administered to prevent hypoglycaemia and not with insulin infusions or in relation to meals." (PMID 36213069, 2022). "There are two main approaches to insulin-glucagon systems: the first utilizes small boluses to prevent hypoglycemia without a concomitant increase in insulin delivery, while the second uses intermittent glucagon doses to allow more aggressive insulin delivery to target lower glucose levels." (PMID 35733769, 2022). "When glucagon fails to be released by the stimulus of hypoglycemia, this defect may be corrected by activation of somatostatin receptor-2 antagonists." (PMID 36992764, 2022).
Hypoglycemia (continued). "Additionally, it has been suggested that excessive delta cell somatostatin secretion in the intra islet milieu augments suppression of alpha cells leading to absent glucagon responses during hypoglycemia." (PMID 34405569, 2021). "In patients with T1D, hypoglycemia failed to increase both copeptin and glucagon." (PMID 34787082, 2021). "This is a scenario specific to hypoglycemia, since other stimuli, including administration of amino acids, insulin withdrawal, lipopolysaccharide exposure and exercise lead to substantial glucagon responses though attenuated compared to nondiabetic individuals in head‐to‐head studies." (PMID 34405569, 2021). "Therefore, we also tested the hypothesis that C-peptide infusion would enhance glucagon secretion and HGP in response to insulin-induced hypoglycemia." (PMID 34003799, 2021). "Finally, neither severe hypoglycemia (event requiring the assistance from another person for administrating carbohydrates and/or glucagon, and/or brief hospitalization) nor diabetic ketoacidosis episode over the 6-month follow-up period was reported." (PMID 33136439, 2021). "The derailed glucagon secretion is not only confined to hypoglycemia as individuals with type 1 diabetes, as opposed to nondiabetic individuals, display glucagon hypersecretion after meal tests, thereby possibly contributing to hyperglycemia and insulin resistance." (PMID 34405569, 2021). "He reported having been administered glucagon injections for hypoglycaemia on numerous occasions which could indicate lack of control of his blood sugar levels." (PMID 33494475, 2021). "It is evident that glucagon concentrations may rise above those observed during hypoglycemia in nondiabetic individuals indicating that alpha cells are highly responsive to amino acids." (PMID 34405569, 2021). "It is well established that glucagon responses to hypoglycemia are absent in type 1 diabetes, but more uncertain whether it is intact following other physiological and metabolic stimuli compared with nondiabetic individuals." (PMID 34405569, 2021). "In an AP system, glucagon will primarily be administered to avoid, not treat, hypoglycaemia." (PMID 32792580, 2020). "Even when glucagon secretion could not be properly stimulated by insulin-induced hypoglycemia in CP related DM patients, preserved catecholamine response to hypoglycemia largely preserved glucose counterregulation." (PMID 33250773, 2020). "Furthermore, emerging evidence has revealed that glucagon secretion and adrenergic mechanisms do not typically play an essential role in this process but are crucial to the recovery from hypoglycemia when glucagon secretion is impaired." (PMID 32328034, 2020). "The stimulants for glucagon release are amino acids, catecholamines, corticosteroids, and intestinal hormones including cholecystokinin, gastrin, and GIP, as well as adrenergic activation in hypoglycemia, whereas glucose and free fatty acids inhibit its release." (PMID 32411223, 2020). "Second, 30-minute, which was the prediction horizon, may be not an enough time to avoid hypoglycemia without the ingestion of carbohydrates or injection of glucagon." (PMID 31694629, 2019). "Interestingly, GIP is known to stimulate glucagon secretion in hypoglycemia and not influence glucagon secretion in hyperglycemia." (PMID 31781045, 2019). "However, genotype did not influence hypoglycemia-induced plasma corticosterone [F = 0.01, p = 0.93], and glucagon responses [F = 1.05, p = 0.32]." (PMID 30996341, 2019). "Moreover, there was no increase in the plasma glucagon levels in response to hypoglycemia at 30 min in the diabetic mice." (PMID 30503832, 2019). "Additionally, the system unleashes an acoustic alarm upon hypoglycaemia re-detection with or without empty glucagon tank." (PMID 30568801, 2018).
Hypoglycemia (continued). "In addition, a biochemical analysis indicated hypoglycemia, without increased serum insulin and C-peptide, but with increased glucagon levels, as the possible influence of glibenclamide overdose." (PMID 30595699, 2018). "Moreover, hindbrain catecholamine projections to the hypothalamus are essential for sympathoadrenal activation and glucagon secretion during slow- but not fast-onset hypoglycemia." (PMID 29593556, 2018). "One major advantage of the automatic treatment of hypoglycaemia by glucagon injection resides in the fact that there are no risks of hyperglycaemia nor side effects that may appear with glucagon injection." (PMID 30568801, 2018). "Glucose levels, however, never reached hypoglycemia, which may be due to a robust glucose counter‐regulation, including glucagon counter‐response which is evident for the incretin hormones, in particular GIP (Malmgren and Ahrén 2015)." (PMID 28611149, 2017). "According to our original hypothesis, GLP-1 should not be able to inhibit glucagon secretion during hypoglycaemia because no somatostatin would be present under these conditions." (PMID 28551699, 2017). "When insulin is given to experimentally induce hypoglycemia in people without diabetes, glucose levels at or below ~3.8 mmol/L will induce a glucagon response, the secretion of which by pancreatic alpha-cells is probably controlled by the neighboring beta-cells." (PMID 26521082, 2016). "ITTs could only be used safely (i.e. without life-threatening hypoglycaemia) to provide a limited decrease in blood glucose levels (to ~ 4 mM), above the usual threshold for substantial glucagon release in the mouse." (PMID 27390586, 2016). "Likewise, there were no apparent differences in glucagon release in response to hypoglycaemia in vivo, nor in vitro in response to low or high glucose." (PMID 26413468, 2015). "When blood glucose levels are low in patients with non-iatrogenic hypoglycemia, insulin secretion is promptly suppressed and counter-regulatory hormones, such as glucagon, catecholamines, cortisol, and growth hormone, are secreted in considerable quantities, elevating the blood glucose level." (PMID 25192953, 2015). "In case of emergency (e.g. symptomatic hypoglycaemia and seizures without a venous access), intramuscular administration of glucagon may be used." (PMID 26316429, 2015). "GLP-1 suppresses glucagon secretion when plasma glucose levels are above fasting level, which is clinically important because GLP-1 loses its inhibitory effect on glucagon secretion at hypoglycemic levels and does not attenuate the counterregulatory responses to hypoglycemia." (PMID 26075286, 2015). "However, it should be noted that other studies have not observed hypoglycemia or postnatal lethality in mice with disrupted glucagon production." (PMID 23977255, 2013). "Furthermore, GLP-1 inhibits glucagon secretion from the pancreatic α-cells at fasting and elevated glucose concentrations, whereas hypoglycemia induced glucagon secretion is not inhibited—the mechanisms involved are not fully understood." (PMID 23543638, 2013). "In non-diabetic adult patients, hypoglycaemia may be related to drugs, critical illness, cortisol or glucagon insufficiency, non-islet cell tumour, insulinoma, or it may be surreptitious." (PMID 22587661, 2012). "Surprisingly, hypoglycemia per se did not increase glucagon release." (PMID 22969729, 2012). "One could speculate that in normal rats, the high doses of antagonist even have some agonist properties, and confirmed that in normal rats, somatostatin is not a major inhibitor of hypoglycemia-induced glucagon release." (PMID 22969729, 2012). "In a non-diabetic adult patient, hypoglycaemia may be related to drugs, critical illness, cortisol or glucagon insufficiency, non-islet cell tumour, insulinoma, or it may be surreptitious." (PMID 22587661, 2012).